LEP (leptin)
Diseases named in the same sentence as LEP in open-access papers (continued):
Sharing a sentence is not in itself a finding about the gene and the disease.
Obesity (continued). "High leptin levels are associated with obesity, insulin resistance, and metabolic syndrome, and conversely elevated plasma adiponectin levels are associated with decreased risk of T2DM, while associations for resistin are contradictory." (PMID 28413567, 2017). "In vitro studies using Leptin or DCA-treatment suggested causal significance of obesity-induced changes in tissue microenvironment in regulating barrier deregulations in tissue-specific manner." (PMID 28698546, 2017). "The mutated genes, related to obesity, include leptin (LEP), leptin receptor (LEPR), pro-opiomelanocortin (POMC) and melanocortin-4 receptor (MC4R)." (PMID 27894098, 2017). "Of interest, the fact that leptin induces autophagy and acts in the pathogenesis of obesity raises the possibility of a role connecting obesity and the development of cancer caused by leptin production." (PMID 28593174, 2017). "In ob/ob mice, which exhibit severe obesity and hepatic steatosis due to the leptin deficiency, Zbtb20 expression was substantially increased in the liver at both mRNA and protein levels compared to lean control." (PMID 28327662, 2017). "Parental BMI was associated with both LEP methylation and obesity-related outcomes and changed the primary association more than 10%; therefore, it was retained in all subsequent models." (PMID 28360946, 2017). "In a model of obesity and type 2 diabetes, feeding oligofructose to leptin-deficient mice decreased the expression of pro-inflammatory cytokines and markers of oxidative stress." (PMID 29017607, 2017). "FTO polymorphism with obesity-related traits has also shown association with increased body weight, leptin levels, and waist circumference." (PMID 28924523, 2017). "As histamine is known to be modulated by leptin and reduced leptin was associated with impulsivity, these finding are in line with the research connecting histamine with obesity–impulsivity axis." (PMID 28243210, 2017). "Given the associations of plasma leptin and adiponectin with (central) obesity, the strong elevations in the L/A ratio in MetS subjects as demonstrated here is not surprising." (PMID 28077136, 2017). "NPY is overproduced in the hypothalamus of leptin deficient ob/ob mice; when depleted by genetic manipulation, ob/ob mice showed reduced food intake, increased energy expenditure and less obesity." (PMID 28489853, 2017). "Our results are consistent with prior studies that reported sex differences in associations of obesity-related outcomes with LEP methylation, and also as would be expected in adipose tissue, the source of circulating leptin." (PMID 28360946, 2017). "Two obesity-related gene polymorphisms (rs7799039, and rs1137101) have been recognized as contributors to BC risk through regulating the level and activity of leptin." (PMID 28938640, 2017). "Although ADCY3 has been associated with locomotor activity, food intake, and leptin sensitivity in mice, the exact mechanisms for its effect on obesity are unclear." (PMID 28763444, 2017). "Clinical and experimental studies indicate an important role of lipocalin-2, FABP4, and leptin as inflammatory adipokines associated with obesity and related complications." (PMID 28757686, 2017). "ChREBP gene deletion protects against high sucrose diet-induced and leptin-deficient obesity, because Chrebp−/− mice cannot consume fructose or sucrose." (PMID 28241431, 2017). "We evaluated the associations of serum adiponectin and leptin with β-cell function and insulin resistance in a population with low obesity prevalence." (PMID 28786989, 2017). "Type 2 diabetic ob/ob mice were used in the present study as the obesity is closely linked to diabetes and rodent models with deficiency in leptin signaling were used as models of obesity and diabetes-related motility disorders." (PMID 28678840, 2017).
Obesity (continued). "Protein tyrosine phosphatase 1B (PTP1B) is known to promote the pathogenesis of diabetes and obesity by negatively regulating insulin and leptin pathways, but its role associated with colon carcinogenesis is still under debate." (PMID 27752061, 2016). "Leptin is a hormone produced by the adipose tissue and is classically increased in type 2 diabetes, but is mostly associated with obesity." (PMID 27141948, 2016). "Obesity presents a chronic, low grade vascular inflammation, caused by macrophage infiltration, increased level of proinflammatory adipokines (leptin, resistin) and cytokines levels (IL-6, TNF alpha), and reduced levels of protective adiponectin." (PMID 27092288, 2016). "In human, mutations of LEP lead to symptoms such as hyperphagia, obesity, hypothyroidism, hyperinsulinemia, hyperlipidemia and hypogonadism." (PMID 27378381, 2016). "Previously, we reported that obesity-induced increases in leptin release cause activation of the STAT3 pathway and result in hepatic expression of CD1417." (PMID 26911834, 2016). "Based on the finding that obese subjects have higher serum levels of leptin and lower levels of its soluble receptor, it has been suggested that human obesity is associated with leptin resistance." (PMID 27240401, 2016). "Any mutations in the LEP gene have an adverse effect on energy regulation pathway and lead to severe, early onset obesity." (PMID 27075752, 2016). "When leptin resistance in the hypothalamus was caused by obesity, the level of serum leptin and the feed efficiency ratio was increased." (PMID 27618865, 2016). "The obesity-related hormone, leptin, is secreted by adipose tissue and has been implicated in the onset and progression of several types of cancer, including colorectal cancer and cancers of the breast, endometrium, and esophagus." (PMID 27050378, 2016). "High-fat diet induced obesity is known to be strongly associated with leptin, which is an adipokine secreted from WAT." (PMID 27599699, 2016). "Leptin concentration in the plasma is positively associated with total fat mass and nearly every measure of obesity in adults." (PMID 28050279, 2016). "Most human obesity and animal models of diet-induced obesity are associated with elevated plasma leptin levels, and the development of resistance to leptin’s body weight lowering actions." (PMID 27609221, 2016). "Taken together, our findings provided an association among obesity hormone leptin, estrogen, and estrogen receptors in HepG2 cells." (PMID 26982332, 2016). "Resistance to the central actions of leptin or insulin is linked to the emergence of obesity and diabetes mellitus." (PMID 27812350, 2016). "Some Leptin G-2548A (rs7799039) polymorphism showed association with serum leptin level and obesity in young females only." (PMID 27703473, 2016). "FIRKO mice, with fat-specific disruption of the insulin receptor gene, have a low fat mass, loss of normal relationship between leptin and bodyweight, protection against hypothalamic lesion-induce obesity and an increase in mean lifespan." (PMID 26945906, 2016). "WAT mRNA expression is increased in human obesity as well as in relevant rodent models, and chronically elevated blood levels of this peptide is known to induce leptin resistance, leading to a loss of appetite suppression and decreased energy production." (PMID 27268060, 2016). "As a result, FADD‐D mutation or adipose‐specific FADD disruption in mice prevents obesity induced by leptin deficiency or by a HFD feeding." (PMID 27357657, 2016). "The metabolic phenotype resulting from central leptin resistance is considered as a pivotal event underlying the development of obesity and its associated dysfunctions." (PMID 27483348, 2016). "Many authors have concluded that leptin resistance plays an important role in hyperphagia and weight gain associated with obesity." (PMID 27579023, 2016).
Obesity (continued). "The ability of leptin to regulate appetite and energy expenditure in rodents with subsequent loss of adipose tissue has led to leptin being termed the anti-obesity hormone." (PMID 26901760, 2016). "Another way to separate the effect of obesity and leptin was attempted by the use of leptin-deficient animals." (PMID 27716333, 2016). "The obesity-linked diabetic phenotype of both mouse strains is caused by a defect in leptin signaling constituting from mutations in leptin (ob/ob mice) or the leptin receptor (db/db mice), respectively." (PMID 27992530, 2016). "Poor lifestyle factors have also been linked to hormonal factors such as reduced levels of leptin, an adipokine strongly linked to appetite and fat storage that increases the risk for obesity." (PMID 27555918, 2016). "We also determined several notable adipokines implicated in obesity and obesity-related metabolic disorders, which included leptin, IL-6, TNF-α, and adiponectin." (PMID 27616737, 2016). "From the age of 8 weeks, central leptin-melanocortin signaling, diabetes, and obesity susceptibility were assessed in male offspring fed a low-fat or high-fat diet for 16 weeks." (PMID 27609221, 2016). "As a result, FADD‐D mutation or adipose‐specific FADD disruption in mice prevents obesity induced by leptin deficiency or by feeding on a HFD." (PMID 27357657, 2016). "First, its cross-sectional design prevented us from identifying cause-and-effect associations between leptin and adiponectin, and blood lipids, obesity and insulin resistance." (PMID 27189377, 2016). "Association of the LEP gene with severe obesity and T2DM have been reported, also case studies in LEP gene malfunction leading to binding-inactive leptin with infantile hyperphagia." (PMID 27147943, 2016). "Orexin-1 receptor antagonist has been shown to exert anti-obesity effects in obese leptin-deficient ob/ob mice." (PMID 28018292, 2016). "The up-expression of Cnr1 in the hypothalamus has been associated with the leptin resistance in obesity." (PMID 28082878, 2016). "It has been suggested that adipocytokine (adipokine) such as leptin is secreted by adipose tissue and concerned with the pathogenesis of obesity-associated complications." (PMID 27630731, 2016). "It is well established that leptin is the adiposity hormone and is closely linked with obesity and its related disorders." (PMID 27990162, 2016). "Except for BF%, WC was the obesity index significantly associated to leptin after control for age and gender." (PMID 27189377, 2016). "Leptin induced obesity states are linked to ROS increase in oxidative stress (Section Inflammation and Arterial Rigidity)." (PMID 27147943, 2016). "Leptin is considered to represent a key player in obesity-associated gastrointestinal malignancies because of its roles in angiogenesis, apoptosis, cell proliferation, and cell migration, which support the milieu of tumor development and progression." (PMID 26839577, 2016). "Obesity is associated with perturbed maternal metabolism, raised plasma hormones, including leptin, insulin, and IGF 1, and the accumulation of inflammatory markers (eg, IL-6)." (PMID 26513002, 2016). "This first report highlights that obesity combines an alteration in oral sensitivity to C18:2 with its association with an increased levels of IL-6 and leptin." (PMID 27413547, 2016). "An association of obesity with cancer is biologically plausible because adipose tissue is metabolically active, secreting estrogens, adipokines (e.g., leptin), and cytokines." (PMID 27472371, 2016). "Hypothalamic Pomc expression is reduced by fasting and in genetic obesity, and transgenic enhancement of Pomc in leptin-deficient mice partially reverses obese phenotypes and completely corrects glucose homeostasis in these mice." (PMID 27832201, 2016). "Elevated serum concentration of leptin has been found in patients with cardiovascular risk factors and obesity status." (PMID 28097156, 2016).
Obesity (continued). "Only eight mutations have been identified in LEP gene at the present causing severe early onset obesity." (PMID 27075752, 2016). "Taken together, diabetes associated with obesity caused feminization, while correction of the diabetes defect by leptin or resveratrol treatment caused re-masculinization." (PMID 26959237, 2016). "Sleep restriction induces a transcriptional reprogramming of white adipose tissue leading to increased lipogenesis, secretion of leptin and food intake, all of them hallmarks of obesity and associated leptin resistance." (PMID 26927084, 2016). "Together, these results suggest that activation of the leptin signaling pathway in the stomach is required to develop obesity-associated atrophic gastritis." (PMID 26839577, 2016). "It has been recently shown that treatment with the antidiabetic drug metformin inhibits excessive ECM deposition in white adipose tissue (WAT) of leptin-deficient ob/ob mice and mice with diet-induced obesity." (PMID 28018292, 2016). "A recent study reports the contribution of the OT system in the alleviation of obesity and reduction of glycemia by retinoic acid treatment in leptin-deficient, ob/ob obese diabetic mice." (PMID 27268060, 2016). "SOCS-3 is a feedback inhibitor of leptin signaling and has been associated with leptin resistance in obesity." (PMID 27547756, 2016). "For example, obesity causes an increase in the blood concentration of leptin, most likely because of increased adipose tissue mass." (PMID 26910012, 2016). "Conversely, the uncontrolled secretion of leptin caused by obesity, inhibits the phosphorylation of CRTC through Ob-R, increasing thus the CP450Arom expression and local production of E2." (PMID 26877711, 2016). "Some of the proposed mechanisms to explain the relationship between sleep and obesity suggest that lower levels of leptin and elevated ghrelin associated with shorter sleep can stimulate appetite and cause weight gain." (PMID 28033380, 2016). "Confirmatory associations were also observed between leptin and obesity, blood lipids and insulin resistance for the first time in an African population." (PMID 27189377, 2016). "We have also demonstrated that mechanical stretch induces the secretion of the obesity-associated hormone leptin from VSMCs and upregulates leptin mRNA expression after 1–3 days of stretch." (PMID 27746739, 2016). "This association of leptin with obesity has been previously demonstrated in a multi-ethnic population including African-Americans, as well as in subjects with various obesity-related pathologies such as in type 2 diabetes." (PMID 27189377, 2016). "Further studies are needed to better elucidate the role of genetics and environment on infant leptin production and risk of obesity later in life." (PMID 27338468, 2016). "One of the mechanisms involved in obesity is associated with mutations in leptin signaling pathway; mutations in leptin (LEP) and leptin receptor (LEPR) gene are associated with obesity in rodents and humans." (PMID 28051281, 2016). "In a low grade inflammation linked to obesity, taste alteration is associated with high levels of IL-6 and leptin." (PMID 27413547, 2016). "Nutritional status and Leptin deficiency can influence the maturation of neuronal projections and glial patterns, and hypothalamic gliosis occurs in mouse models of obesity." (PMID 27080240, 2016). "Diabetes, metabolic syndrome, and obesity are associated with decreased levels of adiponectin and elevated levels of leptin." (PMID 27200209, 2016). "Further studies are needed to better elucidate the role of genetics on infant leptin production and risk of obesity later in life." (PMID 27338468, 2016). "Obesity in children is associated with leptin and insulin resistance, manifested by reduced serum levels of ghrelin and increased leptin and insulin levels." (PMID 26757831, 2016).
Obesity (continued). "Leptin deficiency leads to obesity due to excess energy consumption; however, the FADD‐D mutation enhances energy expenditure to prevent the development of obesity caused by leptin deficiency, resulting in significant abdominal fat reduction." (PMID 27357657, 2016). "The adiponectin-leptin ratio is associated with the risk of obesity-related cancers such as, breast, colorectal, and pancreatic cancers." (PMID 27036040, 2016). "Among cytokines associated with obesity, circulating leptin and resistin levels were reduced in BP3KO mice compared with wild-type mice on HFD, while MCP-1 levels were similar between chow and HFD groups but were significantly lower in BP3KO than WT." (PMID 27448965, 2016). "The interaction between leptin and fat mass and obesity-associated (FTO) gene expression is a major mechanistic pathway underlying the role of leptin in the regulation of body-weigh." (PMID 27189377, 2016). "In previous studies, obesity was shown to be associated with higher levels of leptin in serum and hepatic steatosis after lipid accumulation." (PMID 27618865, 2016). "Leptin deficiency and high-fat diet-induced obesity are associated with increased marrow adipose tissue (MAT) and reduced bone formation." (PMID 27579023, 2016). "Since it was first described in 1994, leptin is the most studied adipokines as well as its association with obesity gene." (PMID 28076486, 2016). "Leptin concentration is highly correlated with fat mass in cats, while the association between obesity and adiponectin in cats is debated." (PMID 27136422, 2016). "Leptin-deficient ob/ob mice exhibit increased food intake, decreased energy expenditure, dyslipidemia, obesity and insulin resistance." (PMID 28025491, 2016). "The pharmacogenetic association of LEPR and LEP to obesity caused by antipsychotics additionally confirms this." (PMID 27673331, 2016). "We also investigated the potential role of the LR gene-related protein (LRGRP) a negative regulator of LRb transport to the cell surface and previously implicated in the development of leptin resistance in diet-induced obesity." (PMID 26926121, 2016). "Deficiency of leptin is associated with lipodystrophy and resistance to obesity, whereas increased C3 is linked to increased central obesity and insulin resistance." (PMID 28031053, 2016). "Animal studies have shown that monosodium glutamate intake increases the risk of obesity, probably through increasing the palatability of food by disrupting the hypothalamic signaling cascade of leptin action." (PMID 27434237, 2016). "LEP gene is a known candidate gene, mutations in which contribute to severe early onset obesity due to the important physiological roles leptin performs in circulation, by ultimately affecting hypothalamus." (PMID 27075752, 2016). "This study confirms the associations previously observed between adiponectin and leptin, and obesity, blood lipids and insulin resistance." (PMID 27189377, 2016). "In conclusion, LEP gene mutations contribute significantly to the monogenic forms of obesity and are important due to the availability of treatment options." (PMID 27075752, 2016). "Conversely, obesity induced overexpression of leptin causes leptin resistance and hence disturbed AHN and depression." (PMID 27429752, 2016). "Whatever its precise role in diet-induced obesity, it is clear that leptin resistance resulting from loss of function of the leptin receptor (db/db mice), in addition to inducing morbid obesity, results in profound negative effects on the skeleton." (PMID 27579023, 2016). "In women with obesity and diabetes, maternal leptin is positively associated with HDL-C but negatively associated with TG." (PMID 27190514, 2016). "Since leptin is closely related to insulin signaling and inflammation, it is considered as a strong risk factor in obesity-related cancer." (PMID 27703473, 2016).